LEPR (leptin receptor)
Diseases named in the same sentence as LEPR in open-access papers (continued):
Sharing a sentence is not in itself a finding about the gene and the disease.
type 2 diabetes (continued). "We also validated that podocytes isolated from kidneys of leptin receptor-deficient (db/db) mice, an established model of type 2 diabetes, exhibited significant downregulation of Tug1 expression compared with podocytes obtained from control nondiabetic (db/m) mice." (PMID 32467232, 2020). "In addition, it was found that empagliflozin can ameliorate cardiovascular injury, vascular dysfunction, and cognitive decline in the context of a mouse model of type 2 diabetes with spontaneous mutation of the leptin receptor." (PMID 30710997, 2019). "The db/db mice, leptin receptor-deficient mice, were chosen as the type 2 diabetes animal model." (PMID 28796243, 2017). "In addition to db/db mice, Zucker diabetic fatty fa/fa (ZDF) rats, harboring a missense mutation (fatty, fa) in the leptin receptor gene (Lepr/ObR), are also widely used as a model of obese type 2 diabetes." (PMID 26937254, 2016). "db/db Mice, homozygous for a point mutation in the leptin receptor gene, are a wildly used genetic model of type 2 diabetes, since they exhibit most of the characteristics of human type 2 diabetes patients, including hyperglycemia, dyslipidemia, and insulin resistance." (PMID 25207824, 2014). "Phase II type 2 diabetes fixed-dose CagriSema (n = 31) demonstrated 15.6 % loss at week 32 with progression of −8.5 % at week four, −13.0 % at week eight, −15.1 % at week 16, and -15.6 % at week 36, showing leptin/soluble leptin receptor ratio differentiation biomarker correlations." (PMID 41255585, 2025). "Secondly, in the db/db mouse model, obesity, insulin resistance and hyperglycemia occur due to leptin receptor deficiency, which is a common research object of type 2 diabetes mellitus (T2DM)." (PMID 41438297, 2025). "Mice homozygous for a mutant allele of the leptin receptor (i.e. BKS-Leprdb/J mice [Leprdb/J]; denoted as db/db) were assessed, given their ability to recapitulate key features of type 2 diabetes." (PMID 38489029, 2024). "In the present study, we investigated the asymmetric responses between the left and right adrenal glands in db/db (leptin receptor-deficit) mice, a commonly used animal model to mimic human type 2 diabetes (T2D)." (PMID 39408986, 2024). "Recent studies have also demonstrated that R. rosea root extracts modulate gut microbiota in a Leptin receptor knockout (db/db) mouse model of type 2 diabetes, in BALB/c mice, and in flies." (PMID 37370698, 2023). "In this study, we investigated the effects of a root extract from Rhodiola rosea in a Leptin receptor knockout (db/db) mouse model of type 2 diabetes." (PMID 35732671, 2022). "LepRdb mice lack the functional, full-length Ob-Rb leptin receptor and can exhibit the characteristics of human type 2 diabetes." (PMID 34796169, 2021). "Other mice models, such as ob/ob mice (leptin mutant) and db/db mice (leptin receptor mutant) are also commonly used as preclinical models of type 2 diabetes." (PMID 34082690, 2021). "The leptin receptor mutant db/db mouse is a commonly used type 2 diabetic mouse model, which manifests syndromes that resemble maturity-onset diabetes in humans." (PMID 31619950, 2019). "The studies conducted in this paper also indicated an average, negative correlation between the concentration of the soluble leptin receptor and the value of the glycated haemoglobin in the blood of people with newly-diagnosed type 2 diabetes." (PMID 28758947, 2017). "The conducted discriminant analysis has also demonstrated that the concentration of the soluble leptin receptor and adiponectin best reflect the influence of the applied therapy on the endocrine activity of the fat tissue in the course of type 2 diabetes." (PMID 28758947, 2017). "A significant decrease in the analysed regulatory molecules, i.e., leptin receptor and adiponectin, was found in blood plasma of the patients with untreated type 2 diabetes." (PMID 28758947, 2017).
type 2 diabetes (continued). "We recently established a novel animal model of obese type 2 diabetes (T2D), the Zucker fatty diabetes mellitus (ZFDM) rat strain harboring the fatty mutation (fa) in the leptin receptor gene." (PMID 25961052, 2015). "We also observed a decreased density of the corneal subbasal nerve plexus and corneal epithelial branches in leptin receptor mutant mice, which are an accepted animal model of type 2 diabetes." (PMID 24696681, 2014). "eNOS−/− mice bred onto the type 2 diabetes db/db line which lack the leptin receptor exhibit even greater DN severity." (PMID 25514595, 2014). "In agreement with our previous study, decreased leptin expression and increased expression of the leptin receptor were also found in the high fat diet plus low dose STZ-induced type 2 diabetic rats, 24–36 hours after chronic exercise." (PMID 24455748, 2013). "We used female leptin receptor-deficient C57BLKS/J-Leprdb/Leprdb mice (BKS-db/db) as a genetic model of type 2 diabetes (T2D), with female non-diabetic mice (BKS-db/m) serving as controls." (PMID 40391966, 2025). "In this study, we compared the features of DPN in vivo using the typical model of type 1 diabetes induced by STZ injection in SD rats and the ZDF rat model of type 2 diabetes, where homozygous missense mutation causes a non-functional leptin receptor." (PMID 36672528, 2022). "In this study, we used leptin receptor-defective db/db mice as a model of type 2 diabetes." (PMID 32340263, 2020). "In type 2 diabetic mice LEP improves hepatic insulin sensitivity by reducing gluconeogenesis which should be associated with the negative correlations between LEPR mRNA vs. glucose and insulin." (PMID 24465964, 2014). "One important intrinsic factor that distinguishes db-derived versus non-db-derived macrophages in this mouse model of type 2 diabetes is the hypomorphic allele of the leptin receptor carried by Lepr−/− mice." (PMID 24057002, 2013). "Increased concentration of sulfate containing bile acids have been observed in feces of mice with nonfunctional leptin receptor, widely used to study type 2 diabetes, which may be associated with an activated pathway to remove elevated fatty acids." (PMID 39863780, 2025). "Unlike the diabetic obese ZDFfa/fa rats, ZDSD rats do not have a leptin receptor mutation, and both sexes develop a type 2 diabetes phenotype of polygenic origin more gradually with age or by induction with a high-fat diet, thus reflecting more closely the pathogenesis of human type 2 diabetes." (PMID 25243714, 2014). "Since leptin receptor sensitivity and food and water consumption were normalized, and fat accumulation and hypertrophic changes in adipocytes were consequently decreased, the voracity of these obese mice with type 2 diabetes may have been inhibited." (PMID 25207824, 2014). "Ob/ob mice that do not express leptin, leptin receptor-deficient db/db mice, and Zucker diabetic fatty rats with a nonfunctional db receptor and a mutation affecting transcription in pancreatic β cells are frequently employed rodent models of type 2 diabetes mellitus (T2DM)." (PMID 32829466, 2020). "We then investigated the functionality of FATS in db/db mice lacking the leptin receptor, which develop type-2 diabetes and show increased lipolysis of endogenous adipose stores, leading to increased levels of circulating FFAs." (PMID 30219861, 2018).
Insulin resistance (150 papers, 2008 to 2025). Increased resistance towards insulin, that is, diminished effectiveness of insulin in reducing blood glucose levels. "A partial LEPR deletion was identified in one patient, associated with severe insulin resistance (second-highest HOMA-IR in the cohort)." (PMID 40429924, 2025). "A study by Mirrakhimo et al27 revealed that the LEPR rs1137101 polymorphism was associated with higher insulin resistance in the Kyrgyz population." (PMID 39136228, 2025). "These mice have a mutation in the leptin receptor gene that leads to insulin resistance and progressive hyperglycemia." (PMID 40287828, 2025). "LEPR rs1137101, the GG genotype is associated with higher BMI, increased calories intake, higher cholesterol and blood sugar level and insulin resistance." (PMID 39203789, 2024). "To characterize insulin resistance due to altered signaling through IRS-1, we employed obese Zucker rats (OZRs), a well-studied genetic model of insulin resistance that exhibits marked hyperinsulinemia due to a leptin receptor mutation." (PMID 36547071, 2022). "There is a direct relationship between body fat levels, leptin, and insulin resistance, with the leptin receptor deficient db/db mouse presenting with alterations in lipid metabolism and liver function including steatosis." (PMID 36992750, 2022). "Despite the global interest in understanding insulin resistance during pregnancy, most genetic studies on leptin and leptin receptor polymorphisms have been conducted in Western or East Asian populations." (PMID 36128550, 2022). "Insignificant association was observed between leptin receptor gene polymorphisms and insulin resistance, and leptin gene and insulin resistant women." (PMID 36128550, 2022). "Perhaps the LEPR c.1968G>C variant is the direct cause of the insulin resistance observed in the study by Wang et. al., and possibly mediates the development of preeclampsia during pregnancy." (PMID 32807109, 2020). "Suppression of hepatic Sdf2l1 expression reportedly results in insulin resistance with sustained ER stress in obese and diabetic db/db mice with leptin receptor mutation." (PMID 32978487, 2020). "The Zucker diabetic fatty rats (ZDF) were established by cross breeding between obese Zucker fa/fa rats and Wistar Kyoto rats, which possess leptin-receptor mutation and insulin resistance, respectively." (PMID 32566684, 2020). "Previous studies have reported that LEPR A668G is associated with impaired glucose tolerance or insulin resistance and T2DM." (PMID 30583468, 2018). "For this, we examined the association of 28 LEPR polymorphisms with body mass index (BMI) and analysed their relationship with biomarkers of insulin resistance, inflammation and cardiovascular disease (CVD) risk in Spanish children." (PMID 28771179, 2017). "But other studies suggested that LEPR Gln223Arg polymorphism was associated with higher insulin resistance and BMI30." (PMID 27034205, 2016). "Other genetic variant at the LEPR locus (rs3790433) was also associated with increased risk of metabolic syndrome and insulin resistance in adults with metabolic syndrome." (PMID 27240401, 2016). "The C57BLKS/J (db/db) model is obese via a mutation in the leptin receptor, develops insulin resistance very quickly and has progressive β-cell depletion." (PMID 26198986, 2015). "Previous studies reported LEPR polymorphisms were associated with glucose metabolism and insulin resistance, possibly leading to a predisposition towards greater MS risk." (PMID 24444121, 2014). "The db/db mouse (BKS.Cgm+/+Leprdb/j) is a genetic model widely used as MS animal model, as it presents a leptin receptor mutation which causes hyperglycemia and insulin resistance." (PMID 23691518, 2013). "The LEPR is an adipocytokine receptor that is involved in the regulation of fat metabolism and has been associated with insulin resistance, a key feature of MetS." (PMID 23306188, 2013).
Insulin resistance (continued). "LEPR (leptin receptor) resistin (RETN) is associated with insulin resistance, T2D, CVD, and PCOS." (PMID 39859066, 2025). "Thus, we conclude that TNF-α disrupts the regulation of leptin on the β cell GSIS function by inhibiting leptin receptor LepRb and thus producing excessive insulin secretion related to hyperinsulinemia, which is postulated to be a cause of insulin resistance." (PMID 35198097, 2022). "Indeed it has been shown that specifically restoring hypothalamic leptin action in leptin receptor deficient rats improved whole body insulin resistance by enhancing hepatic insulin sensitivity." (PMID 27273128, 2016). "Homozygosity for the LEPR rs3790433 G allele was associated with insulin resistance, which may predispose to increased MetS risk." (PMID 23306188, 2013). "The goal of the study was to examine if there was a link between the leptin (LEP)/leptin receptor (LEPR) gene polymorphism and insulin resistance in pregnant women, and to determine the extent to which the leptin gene polymorphism could cause insulin resistance." (PMID 36128550, 2022). "The goal of the study was to examine if there was a link between the leptin (LEP) (rs77990) as well as LEPR gene (rs1137101) with insulin resistance and lipid profile, in order to determine the extent to which the leptin gene polymorphism could cause insulin resistance in pregnant women." (PMID 36128550, 2022). "Therefore, it is suggested that this variant of LEPR polymorphism may carry a risk of insulin resistance and liver steatosis in later life." (PMID 27240401, 2016). "Homozygosity for the leptin receptor (LEPR) rs3790433 G allele was also associated with increased MetS risk, which may be accounted for by increased risk of elevated insulin concentrations and insulin resistance." (PMID 23306188, 2013). "Transcriptome results identified many DEGs linked to insulin resistance, fatty acid β oxidation, and inflammation, including IGF2BP2, LEPR, RAP1A, SESTRIN 3, and ITLN1 that have also been reported in human T2DM." (PMID 40878918, 2025). "Increases in insulin resistance, leptin levels, and soluble leptin receptor levels, alongside declines in fasting glucose and adiponectin levels during pregnancy, were consistent with findings in both normal weight and obese cohorts in these studies." (PMID 41202005, 2025). "The leptin receptor (LEPR), which was predicted to be the target of miR-6899-3p, plays a significant role in liver insulin resistance." (PMID 39823117, 2025). "Two main populations of neurons, POMC and AgRP, express leptin receptor and insulin receptor, and insulin action in these neurons affected systematic insulin resistance." (PMID 36042571, 2023). "In comparison to other genotypes, persons with homozygous dominant, 'GG' of LEPR had increased insulin resistance and hyperinsulinemia." (PMID 36128550, 2022). "Due to the dysfunction of the leptin receptor, db/db mice spontaneously develop hyperphagia-induced hyperglycemia, insulin resistance, and dyslipidemia." (PMID 34233739, 2021). "Studies showed that the db/db mouse model, which carries mutated leptin receptor, exhibited metabolic syndrome of T2DM (such as hyperglycemia, overweight, dyslipidemia, insulin resistance, and inflammation), also accompanied with cognition impairment symptoms." (PMID 34975464, 2021). "Since leptin insufficiency is associated with metabolic disease and insulin resistance, we would expect metabolic abnormalities in LEP/LEPR wt/-." (PMID 34448070, 2021). "Since this phenotype is not observed in the mice with ablated GHR in the AgRP/NPY, POMC and VMH neurons, it is likely that other LepR-expressing cells mediate the insulin resistance of the mice with diminished GHR signaling in the LepR cells." (PMID 31939479, 2019). "More importantly, we found that, in the β cells of db/db mice with severe insulin resistance that was due to a defect in leptin receptor, there was a significantly increased proinsulin misfolding." (PMID 31311313, 2019).
Insulin resistance (continued). "Indicating role played by Gln223Arg in LEPR in influencing the insulin resistance in obese group of Saudi women." (PMID 30763324, 2019). "We nest sought to extend these observations from cellular models to in vivo models of insulin resistance, the HFD-induced insulin resistant mice and the leptin receptor-deficient db/db mice." (PMID 30666198, 2018). "In that light, the excess cytokine gene expression in the ovary of IR/LepR mice (Insulin resistance and leptin receptor) is interesting." (PMID 29201665, 2017). "The leptin receptor and leptin defects result in an obese phenotype that leads to insulin resistance, glucose resistance and hyperglycemia." (PMID 28640857, 2017). "Due to the expression of a mutant leptin receptor, db/db mice show severe leptin resistance and insulin resistance." (PMID 24614172, 2014). "In the present study, we evaluated the association between 4 insulin resistance genes (ADIPOQ, LEPR, RETN, and TRIB3) and both T2DM and hypertension." (PMID 24414038, 2014). "We found that Gcn2 deficient mice display the same HiS/LoH triglyceride phenotype and also exhibited increased hyperglycemia and insulin resistance when genetically combined with leptin receptor mutant (db/db)." (PMID 24130751, 2013). "One adipokine, leptin, is typically positively correlated with fat mass, however in the ZDF model of extreme insulin resistance and a defective leptin receptor, this correlation is lost, a finding confirmed in the present experiment (r=0.0703, p=0.65)." (PMID 23146593, 2012). "However, both groups of women displayed a similarly large increase in insulin resistance and alterations in levels of adipokines, such as increased leptin and soluble leptin receptor (LepR)." (PMID 41202005, 2025). "Lepr db/db mice have an autosomal recessive mutation in the leptin receptor with nonfunctioning and insensitive leptin receptors, resulting in the development of hyperglycemia, hyperinsulinemia, obesity, and insulin resistance in 4–8 weeks." (PMID 40649774, 2025). "Leptin resistance and impaired LEPR signaling contribute to the development of hepatic insulin resistance and are associated with several conditions, such as nonalcoholic fatty liver disease (NAFLD)." (PMID 39823117, 2025). "Further analysis determined that broad inhibition of selenoprotein synthesis caused oxidative damage to leptin receptor (LEPR)-expressing POMC neurons, which the authors hypothesized was a key factor in the development of leptin and insulin resistance." (PMID 36499772, 2022). "The higher expression of LEPR in our opioid-exposed male cohort may induce a hyperleptinemia state that triggers insulin resistance and cardiometabolic complications." (PMID 35127598, 2021). "We observed that LepR reactivation in adult animals caused insulin resistance, without impairing glucose tolerance of Ubi-LepRNull mice." (PMID 30694175, 2019). "Furthermore, mice with genetic insulin resistance in liver increase hepatic expression of LEPR and demonstrate an 80-fold increase in circulating forms of LEPR." (PMID 30224299, 2018). "Compared with leptin or leptin receptor mutated diabetic animal model, our model showed the superiority by endowing animal typical insulin resistance without the interference of leptin deficiency on healing." (PMID 27028201, 2016). "In addition, the administration of exogenous IL-22 in genetically obese leptin-receptor-deficient (db/db) mice and mice fed with HFD reverses many of the metabolic symptoms, including hyperglycemia and insulin resistance." (PMID 26681840, 2015). "Identification of a null mutation in the leptin receptor gene in the SHR-ob rats suggests that these animals exhibit insulin resistance resulting from the absence of leptin receptors." (PMID 22963383, 2012). "In addition, antisense-RNA mediated adipocyte-specific reduction of LEPR leads to decrease in LEPR signaling, resulting in increased adipocyte, hypertriglyceridemia, and insulin resistance." (PMID 20624279, 2010).